KRAS (KRas proto-oncogene, GTPase)
Diseases named in the same sentence as KRAS in open-access papers (continued):
Sharing a sentence is not in itself a finding about the gene and the disease.
colorectal cancer (continued). "Different dilutions (0, 0.1, 0.5, 1, 5, and 100%) of the DNA isolated from the human colorectal cancer cell line LS174T that carries the mutated (G12D) KRAS allele within the context of unmutated DNA isolated from the human cell line Caco2 (normal KRAS) were prepared." (PMID 35200357, 2022). "KRAS mutations have been well characterized in 30%–50% of colorectal cancers." (PMID 36330448, 2022). "Murine models of KRASG12D colorectal cancer have shown that upregulation of signaling in the MAPK pathway with oncogenic KRAS mutations promotes tumor dedifferentiation for which TGFβ signaling may compensate against tumorigenesis." (PMID 36382087, 2022). "Therefore, clinicopathological and molecular characteristics of colorectal carcinoma with KRAS/BRAF double mutations are unclear." (PMID 35280113, 2022). "KRAS mutation is more common than NRAS mutation in colorectal carcinoma." (PMID 35328664, 2022). "Mutated KRAS is reported in approximately 35%-45% of colorectal cancers and >90% of pancreatic ductal adenocarcinoma (PDAC) correlating with abnormal metabolic rates, enhanced glucose uptake and resistance to EGFR-targeted therapies as well as preoperative chemoradiotherapy (CRT) 8-10." (PMID 33664850, 2021). "KRAS gene is the most common type of mutation reported in colorectal cancer (CRC)." (PMID 33413474, 2021). "One recent study showed that the combination of IF and vitamin C was a promising intervention with low toxicity, which could be tested in randomized clinical trials against colorectal cancer and possibly other tumors with KRAS mutations." (PMID 33628585, 2021). "Results showed that patients with mutated KRAS colorectal cancer had 3 times the risk of developing thrombotic events as those with unmutated KRAS, making it the first study that showed the implication of a genetic mutation on the risk of developing thrombosis." (PMID 32885400, 2021). "Furthermore, we review the impact of KRAS colorectal cancer mutants on pathway rewiring associated with disruption and dysfunction of the normal intestinal homeostasis." (PMID 33691728, 2021). "In KRAS mutated colorectal cancer cells the pentose phosphate pathway has been demonstrated to be essential for the growth in aerobic conditions and glutamine conversion into α-ketoglutarate and alanine aminotransferase for KRAS induced anchorage-independent growth." (PMID 33777798, 2021). "Notably, LKB1 regulation of ALKBH5 via 5mC-DNA was not limited to KRAS mutant lung cancer, but extended to pancreatic and colorectal cancer, which are the top three causes of cancer death in the United States34." (PMID 34016959, 2021). "We examined and analyzed mutation status of KRAS/NRAS/ BRAF in colorectal cancer tissues." (PMID 33816307, 2021). "Interestingly, more than 40% of colorectal cancers harbor KRAS mutation, resulting in the continuous activation of its downstream Raf–MEK-ERK signaling pathway and malignant transformation." (PMID 34345014, 2021). "Furthermore, LKB1 expression negatively correlated with ALKBH5 expression was also found in KRAS-mutated pancreatic and colorectal cancer cell lines." (PMID 34016959, 2021). "KRAS mutational heterogeneity between primary colorectal cancer and liver metastases may present a challenge in assessing prognostic information prior to the multimodal treatment." (PMID 33946899, 2021). "KRAS status was significantly associated with HPD in patients with colorectal cancer." (PMID 34239621, 2021). "The KRAS oncogene, which is mutated in 15–30% of lung cancers, in 90% of pancreatic cancers and in 30–40% of colorectal cancers is one of the main driver mutations in these severe cancer forms, which are causes of significant public health burden and mortality." (PMID 34781949, 2021). "Besides lung, another cancer type that shows high frequency of KRAS mutations is colorectal cancer (CRC), with some studies indicating 40% rates." (PMID 34684076, 2021).
colorectal cancer (continued). "The aim of this study was to retrospectively analyze whether the PIK3CA and KRAS mutational status had an impact on overall survival in patients with colorectal cancer and aspirin use." (PMID 34638442, 2021). "BRAF and KRAS mutations are considered drivers of the formation of serrated colorectal cancers." (PMID 33919924, 2021). "In clinical settings, PBK/TOPK expression is an unfavorable prognostic indicator in patients with sporadic colorectal cancer with mutations in the proto-oncogene KRAS or BRAF and in patients with metastatic disease experiencing a response to anti-EGFR monoclonal antibody therapies." (PMID 33670114, 2021). "KRAS mutations are commonly detected in pancreatic cancer, colorectal cancer and NSCLC." (PMID 34885068, 2021). "More than half of all colorectal cancer patients with ovarian metastases harbor KRAS mutations." (PMID 34367398, 2021). "KRAS is one of the most widely mutated oncogene in human colorectal cancers (CRCs)." (PMID 34003553, 2021). "To this end, we compared the metabolic profiles of the parental KRASG13D/+ (parental line isolated from a colorectal cancer patient in which glycine (G) 13 is mutated to aspartate (D)) and its isogenic derivative cell lines KRAS+/– and KRASG13D/– in human colon cancer cells (HCT116)." (PMID 34822010, 2021). "Colorectal cancer is a highly prevalent cancer type that often harbours KRAS mutations." (PMID 34781949, 2021). "However, by using AFM, Mouliere and colleagues showed that 80% of ccfDNA in colorectal cancer patients is <145 bp and, by qPCR, that the ccfDNA with KRAS mutation is more fragmented than the wild-type ccfDNA in colorectal cancer patients." (PMID 34109115, 2021). "Furthermore, it is well known that mutations in proteins of the MAPK pathway, such as BRAF or KRAS, are involved in the initiation and progression phases of colorectal cancer." (PMID 33691728, 2021). "The KRAS A146 mutation is predominantly seen in patients with colorectal cancer." (PMID 34820593, 2021). "The inhibition of PBK/TOPK could benefit those colorectal cancer patients with a KRAS or BRAF mutation and those with metastasis, which represented 30–40% of all cases, and this may represent a new avenue of investigation for targeted therapy." (PMID 33670114, 2021). "Missense KRAS mutations have been found in 40%–45% of colorectal cancer patients, while mutations affecting the activity of Wnt/β-catenin were detected in over 80% of colorectal cancer patients." (PMID 34577571, 2021). "However, prognostic data on aspirin use after a colorectal cancer diagnosis in relation to KRAS mutational status is limited." (PMID 34638442, 2021). "In this review, we focus on the special role of KRAS mutations in colorectal cancer (CRC), aiming to collect recent data on KRAS-driven enhanced cell signalling, in vitro and in vivo research models, and CRC development-related processes such as metastasis and cancer stem cell formation." (PMID 33802849, 2021). "This is in accordance with a previous molecular study of matched tumor pairs/trios of colorectal cancer patients with ovarian metastases, suggesting that mutated KRAS is a universal driver of the metastatic disease in women with KRAS-mutated colorectal cancer with ovarian metastases." (PMID 34367398, 2021). "Previous studies have shown that KRAS mutations play an essential role in the metastasis of colorectal cancer, and speculated that KRAS mutations might be the driving factor for their successful implantation." (PMID 34367944, 2021). "In vitro experiments indicated that MRTX1133 has a dose-dependent inhibition of the KRAS signalling pathway activity and significantly reduced the size of tumours with KRAS G12D mutations in pancreatic and colorectal cancer models compared with the control group." (PMID 34012925, 2021).
colorectal cancer (continued). "However, some reports suggest that KRAS G13D mutant colorectal cancer is associated with an improved outcome after treatment with the anti-EGFR antibody cetuximab compared to responses observed for other KRAS mutations." (PMID 34680229, 2021). "The aim of this work was to examine whether PIK3CA mutational status and KRAS mutational status could indeed augment the effect of aspirin on the survival of patients with colorectal cancer." (PMID 34638442, 2021). "For lung cancers, EGFR mutations have been linked with decreased cytotoxic T cell infiltration, whereas for colorectal cancers, KRAS mutations have been associated with increased marrow-derived suppressor cell infiltration and the subsequent decreased infiltration of cytotoxic T cells." (PMID 34108525, 2021). "KRAS is an oncogene that is mutated in more than 40% of human colorectal cancer cases." (PMID 33627125, 2021). "However, colorectal cancer cell lines with KRAS/BRAF mutations exhibited increased GLUT1 expression, independent of HIF1α status in normoxic conditions." (PMID 33420213, 2021). "For example, SLC25A22, a glutamate carrier that facilitates the transport of glutamate across the IMM into the mitochondria matrix, promotes cell proliferation and tumor progression of colorectal cancer with KRAS mutations via intracellular synthesis of aspartate." (PMID 34568013, 2021). "KRAS was the most commonly mutated oncogene in lung, pancreatic, and colorectal carcinomas and enabled an improved rate of glutathione regeneration and ferroptosis protection by elevating nicotinamide adenine dinucleotide phosphate hydrogen levels through metabolic reprogramming." (PMID 35096011, 2021). "Moreover, mutations in KRAS are found in exon-4 (p.A146, p.K117) in approximately 4% of primary colorectal cancers and in 10% of colorectal cancer cell lines, as well as in a few MM patients and in the MM cell line AMO1." (PMID 32079091, 2020). "Urine DNA analysis has determined mutations in KRAS in pancreatic and colorectal cancers." (PMID 32294884, 2020). "Currently, KRAS mutation occurs in 30–50% of colorectal cancers." (PMID 32793499, 2020). "Approximately 32–40% of colorectal cancers harbour a KRAS mutation." (PMID 33183271, 2020). "We hope the results of this study could be used as a reference for the future use of liquid biopsy in KRAS mutation detection in colorectal cancer by clinicians and researchers." (PMID 32590745, 2020). "KRAS or BRAF mutations that occur in colorectal cancer may also contribute to glucose uptake and GLUT1 overexpression." (PMID 33352824, 2020). "However, nutrient utilization generally was varied among colorectal cancer cell lines with different KRAS mutations." (PMID 32300895, 2020). "In support of a potential role of ferritin in colorectal cancer progression, an analysis of The Cancer Genome Atlas Database indicates that KRAS mutated colorectal cancer patients with low intratumor ferritin mRNA levels display longer 3- and 5-year overall survival." (PMID 32393788, 2020). "Mutations in the Kirsten Ras (KRAS) oncogene occur in 30–40% of colorectal cancers (CRCs) and have been associated with poor prognosis and resistance to anti-epidermal growth factor receptor (EGFR)-targeted cancer therapy such as the monoclonal antibody panitumumab." (PMID 32300895, 2020). "A major oncogenic driver in colorectal cancer is KRAS with an average mutation rate of 40%." (PMID 32725342, 2020). "Therefore, it is of great clinical value of differentiating KRAS mutations to provide guidance of individualized treatments of colorectal cancer patients." (PMID 32207862, 2020). "Resistance to prenylation inhibitors of KRAS mutant colorectal cancer may be partly due to increased stability of K-Ras proteins mediated by mutations in WNT signaling pathway." (PMID 32524209, 2020).
colorectal cancer (continued). "As KRAS is one of the most important mutated genes in colorectal cancer, we hypothesized that patients harboring KRAS mutant fragments may have a poor clinical phenotype." (PMID 32379795, 2020). "Mutations in KRAS were most frequently identified in colorectal cancers, followed by lung cancers." (PMID 32087721, 2020). "Modern diagnostics for colorectal cancer detect mutations in KRAS, NRAS, and EGFR genes." (PMID 32774122, 2020). "Since KRAS mutations occur frequently in colorectal cancer, we asked whether KRAS mutation enrichment in the P4HA1-high group may contribute to poor prognosis in early stage CRC." (PMID 32166002, 2020). "Interestingly, KRAS-mutated colorectal cancer patients display significantly higher levels of asparagine synthetase enzyme with respect to wild-type KRAS patients." (PMID 32932943, 2020). "Finally, APC mutations in colorectal cancer, KRAS in gastric cancer, and pancreatic cancer were mostly associated gene alterations." (PMID 33127962, 2020). "The KRAS mutation is, for example, predictive of Cetuximab efficacy in colorectal cancer." (PMID 31936310, 2020). "In addition, CRISPR-mediated deletion of ARID1A in human colorectal cancer cells with KRAS mutations significantly reduced proliferation, accompanied by attenuation of MEK/ERK dependent transcriptional signaling." (PMID 32967217, 2020). "Point mutation rate of KRAS gene is 40%‐50% in colorectal cancer." (PMID 32207862, 2020). "Well established examples include KIT mutations which are present in ~ 85% of gastro-intestinal stromal tumors, EGFR mutations that have been identified in ~ 15% of non-small cell lung cancers, and lung and colorectal cancers with mutations in the KRAS oncogene." (PMID 32087721, 2020). "Furthermore, this study highlights that colorectal cancer cells carrying different KRAS mutations exhibit specific metabolic phenotypes, including differences in glycolysis, glutamine utilization, and amino acid, choline and nucleotide hexosamine metabolism." (PMID 32300895, 2020). "Moreover, colorectal cancers with KRAS mutations are often resistant to cetuximab, which is a major drug used in the therapy of these cancers." (PMID 33352824, 2020). "Recently, a preclinical study reported that cancer cell-selective toxicity of AA in colorectal cancer with KRAS and BRAF mutation could be enhanced by induction of GLUT-mediated cellular uptake of DHA." (PMID 33071784, 2020). "KRAS G13D mutations were observed to account for approximately 16% of all KRAS mutations in advanced colorectal cancer patients, and whether these patients can benefit from cetuximab has not been determined." (PMID 32404198, 2020). "There are some data about patients with synchronous metastasized colorectal cancer which might have a higher rate of discordance in the KRAS mutation status." (PMID 33002027, 2020). "Next, the most active derivatives were studied in MCF-7 (breast adenocarcinoma, Ras/RAF wild type, and PIK3CA mutant), HeLa (cervical carcinoma, Ras/RAF and PIK3CA wild type), as well as HCT-116 and HKH-2 (colorectal carcinoma, KRas mutant and mutated KRas disrupted, respectively) cell lines." (PMID 33371382, 2020). "We have shown how transcriptional adaptation is ultimately responsible for PI3K activation upon vertical suppression of the EGFR/MAPK pathway through the upregulation and cooperative activation of different RTKs in a preclinical model of KRAS-mutated colorectal cancer." (PMID 30691487, 2019). "Development of a preclinical animal model that mimics KRAS mutated colorectal cancer is urgent." (PMID 31766149, 2019). "Furthermore, we analyzed differential expression of TP73 in colorectal cancer tissues based on age, sex, site, and KRAS mutation status." (PMID 31090204, 2019).
colorectal cancer (continued). "Furthermore, 6/9 KRAS G12 mutations in treatment-naïve patients were from either pancreatic or colorectal cancers." (PMID 31546879, 2019). "In addition, ERH expression is inversely associated with the survival of colorectal cancer patients whose tumors harbor KRAS mutations." (PMID 30866868, 2019). "Furthermore, this strategy has been successfully applied for detection of a KRAS mutation from tissue samples of colorectal cancer patients." (PMID 30976068, 2019). "For instance, in colorectal cancer, skewness was negatively correlated with KRAS mutation." (PMID 31174617, 2019). "Also longitudinal cfDNA analysis has been used in colorectal cancer patients for monitoring of cetuximab resistance through acquisition of secondary KRAS mutations and also resistance to antiangiogenic therapies." (PMID 31817150, 2019). "Furthermore, loss-of-function mutations in adenomatosus polyposis coli is associated with CSC activation via β-catenin activation and enhancement of KRAS mutation in colorectal cancer tumorigenesis." (PMID 31428052, 2019). "This hypothesis was supported by the finding that KRAS mutations synergize with aberrant Wnt signaling in colorectal cancer to activate cancer stem cells." (PMID 31213486, 2019). "In addition, patients with colorectal cancer harboring KRAS, BRAF or PIK3CA mutations have poor prognosis compared to patients without these mutations." (PMID 31769426, 2019). "For instance, in colorectal cancer cells, mutation of KRAS has been shown to influence exosomal cargo through an nSMAse-dependent mechanism, with mutant KRAS cells loading preferentially a greater amount of miR-100, whereas wild-type KRAS cells package higher levels of miR-10 in the exosomes." (PMID 31546654, 2019). "Moreover, we will examine the enhanced the cell death by combined treatment with perifosine and trametinib or PD0325901 in other human colorectal cancer cell lines harboring KRAS, BRAF and PIK3CA mutation." (PMID 31769426, 2019). "In summary, widening the KRAS mutational and subtyping analysis of colorectal cancer patients beyond the KRAS ‘hotspot’ codons 12 and 13 is useful in identifying patients who should not be treated with anti-EGFR antibodies, either alone or in combination with other anticancer agents." (PMID 31881025, 2019). "Moreover, the developed strategy can also be successfully applied for the detection of KRAS mutation from tissue samples of colorectal cancer patients, presenting a promising application for ultrasensitive detection of mutation in clinical diagnosis." (PMID 30976068, 2019). "In mouse models of colorectal cancer, while primary tumors were characterized by a heterogeneous population of cells bearing both oncogenic KRAS mutations and wild-type KRAS, metastatic sites were largely comprised of more uniform cell populations harboring oncogenic KRAS." (PMID 31681559, 2019). "Oncogenic mutations in KRAS or BRAF are frequent in colorectal cancer and activate the ERK kinase." (PMID 31266962, 2019). "BRAF and KRAS mutations have been associated with increased in glucose uptake, lactate production and phosphoserine biosynthesis suggesting a shift toward glycolysis pathway in colorectal cancer." (PMID 31835496, 2019). "p.G12D, p.G12V, and p.G13D were the most common KRAS mutations in our cohort of colorectal cancers." (PMID 31036005, 2019). "KRAS-mutated colorectal cancers (CRCs) are resistant to cetuximab treatment." (PMID 31010234, 2019). "Through functional analysis, we have confirmed that TNS4 is significantly downregulated by cetuximab in a subset of colorectal cancer cell lines including KRAS activating mutations, suggesting that TNS4 may be one of the pharmacological targets of cetuximab." (PMID 31409052, 2019).